PPEF2 (protein phosphatase with EF-hand domain 2)
Description:
May play a role in phototransduction. May dephosphorylate photoactivated rhodopsin. May function as a calcium sensing regulator of ionic currents, energy production or synaptic transmission.
Synonyms: PPP7CB
Tractability: PROTAC: ubiquitination databases record sites on it.
Gene: Protein-coding gene on chromosome 4 (75,859,864 to 75,902,571, reverse strand). Ensembl gene ENSG00000156194.
Subcellular location: Cytoplasm; Cell projection, cilium, photoreceptor outer segment; Photoreceptor inner segment
Gene Ontology:
Molecular function: Hsp70 protein binding; Hsp90 protein binding; mitogen-activated protein kinase kinase kinase binding; protein serine/threonine kinase inhibitor activity; protein serine/threonine phosphatase activity; calcium ion binding; hydrolase activity; iron ion binding; manganese ion binding; phosphoprotein phosphatase activity
Biological process: cellular response to hydrogen peroxide; negative regulation of apoptotic signaling pathway; negative regulation of MAPK cascade; protein dephosphorylation; detection of stimulus involved in sensory perception
Cellular component: cytoplasm; photoreceptor inner segment; photoreceptor outer segment
Genetic constraint (gnomAD): Loss-of-function variants: 72 observed, 69.82 expected, observed/expected ratio (o/e) 1.03, 90% interval 0.85 to 1.25. The upper end of that interval is the gene's LOEUF score, 1.25, which puts it in group 5 of 6, group 1 being the genes least tolerant of losing a copy. Missense variants: 838 observed, 880.89 expected, observed/expected ratio (o/e) 0.95, 90% interval 0.9 to 1.01. Synonymous variants: 321 observed, 333.74 expected, observed/expected ratio (o/e) 0.96, 90% interval 0.88 to 1.05.
Homologues: Orthologues: chimpanzee PPEF2 (99% identical), macaque PPEF2 (96% identical), rabbit PPEF2 (85% identical), rat Ppef2 (84% identical), mouse Ppef2 (83% identical), pig PPEF2 (78% identical), dog PPEF2 (73% identical), guinea pig PPEF2 (69% identical), tropical clawed frog PPEF2 (62% identical), zebrafish PPEF2 (49% identical), Caenorhabditis elegans pef-1 (38% identical), Drosophila melanogaster rdgC (36% identical), and 28 more. Paralogues in human: PPEF1 (42% identical), PPP5C (21% identical), PPP3CB (18% identical), PPP3CA (18% identical), PPP3CC (18% identical), PPP1CC (15% identical), PPP1CB (14% identical), PPP2CB (14% identical), PPP1CA (14% identical), PPP2CA (14% identical), PPP4C (14% identical), PPP6C (12% identical).
Diseases named in the same sentence as PPEF2 in open-access papers:
PPEF2 is named in the same sentence as 13 diseases in open-access papers, as found by Europe PMC text mining. Sharing a sentence is not in itself a finding about the gene and the disease. The quoted sentences say what the papers report.
asthma (1 paper, 2014). "Lastly, in the Asthma BRIDGE replication population, we evaluated the relation between DNA methylation and expression for XPNPEP1, PPEF2, and FRMD4 as well as the association between IUS and expression." (PMID 24964093, 2014). "XPNPEP1 and PPEF2 are two genes that may also be of interest as they were significant in both the CAMP and Asthma BRIDGE populations." (PMID 24964093, 2014).
breast carcinoma (1 paper, 2022). "PPP1CC, PPP5C and PPEF2 were not aberrantly expressed in breast cancer tissues." (PMID 34964699, 2022).
breast tumors (1 paper, 2012). "Additionally, a number of prosurvival (BCL2, PPEF2) and proapoptosis (BID, HEBP2, and PKNOX1) genes were up- and downregulated, respectively, in bone metastases compared with primary breast tumors." (PMID 23174366, 2012).
pancreatic adenocarcinoma (1 paper, 2021). "PPEF1 and PPEF2 showed low expression in both pancreatic adenocarcinoma and normal tissues in this work." (PMID 33270085, 2021).
pancreatic cancer (1 paper, 2021). "In contrast, patients with pancreatic cancer and high transcription levels of PPP3CB, PPP5C, PPP6C, and PPEF2 seemed to have better prognosis." (PMID 33270085, 2021). "However, we found that PPEF2, rather than PPEF1, demonstrated a favorable prognostic value at the mRNA level in pancreatic cancer." (PMID 33270085, 2021).
retinal degeneration (1 paper, 2019). Degeneration of the retina. "In mice, Ppef2 is strongly expressed in the retina, but Ppef2 deficiency did not cause retinal degeneration, while Ppef2-orthologs prevent retinal degeneration in Drosophila." (PMID 30809231, 2019).
infection (1 paper, 2019). The state of being infected such as from the introduction of a foreign agent such as serum, vaccine, antigenic substance or organism. "In the case of an infection, exposure of cDC1 to TLR-ligands also down-regulates Ppef2-expression in mature DCs." (PMID 30809231, 2019). "As infection models with pathogens or protein immunization with adjuvants contain TLR-signals which rapidly downregulate Ppef2 in Ppef2+/+ DCs, such models render Ppef2−/− and Ppef2+/+ mice quite similar with respect to low Ppef2-levels." (PMID 30809231, 2019).
neurological disorder (1 paper, 2015). "However, as a note of interest, these CNVs included the NDUFB3, NIF3L1, PPEF2, CACNA2D1 and GPC5 genes, which are expressed in the brain and/or have been implicated in neurological disorder." (PMID 25585696, 2015).
PPEF2 also shares sentences with these, for which no sentence is quoted: schizophrenia (2 papers); autism (1); psychiatric disorder (1); retinitis pigmentosa (1); tumor (1).